GLI1 (GLI family zinc finger 1)
Diseases named in the same sentence as GLI1 in open-access papers (continued):
Sharing a sentence is not in itself a finding about the gene and the disease.
mesothelioma (continued). "To further our understanding of the concurrent expression of Cul4A and Gli1 in mesothelioma samples, we investigated whether Gli1 expression can be regulated by Cul4A levels in human mesothelioma cell lines." (PMID 26218750, 2015). "In recent studies of the importance of Gli1 expression in mesothelioma tumours, Gli1 transcription and protein expression were increased significantly in mesothelioma tumours when compared to normal pleural tissues 8,9, and high Gli1 expression was significantly associated with poor survival." (PMID 26218750, 2015). "Furthermore, we demonstrated that Gli1 expression and transcriptional activity were down-regulated after CK2α was silenced in two mesothelioma cell lines (H28 and H2052)." (PMID 25422081, 2014). "Furthermore, in the experimental studies of mesothelioma cell lines, CK2α was suggested to positively regulate Hh/Gli1 signaling." (PMID 25422081, 2014). "Thus, we report for the first time that over-expressed CK2α positively regulate Hh/Gli1 signaling in human mesothelioma." (PMID 25422081, 2014). "The relationship between CK2 and Hh/Gli1 signaling in other types of cancer, including mesothelioma is still unknown." (PMID 25422081, 2014). "In this study, correlated IHC staining of CK2α and Gli1 in mesothelioma was demonstrated." (PMID 25422081, 2014). "Recently, Hh/Gli1 signaling was reported to be aberrantly activated in human mesothelioma." (PMID 25422081, 2014). "This study evaluated the factors affecting the development of malignant mesothelioma, proposed a new idea of SMO, GLI1, and immune cells as possible indicators of personalized immunotherapy and prognosis, and provided an experimental basis for finding new gene targets for mesothelioma." (PMID 37139482, 2023). "Further study on the expression and prognosis of SMO and GLI1 in malignant mesothelioma tissues and the relationship between the two and the molecular mechanisms of mesothelioma immunity and to further investigate the prognostic value of mesothelioma expression." (PMID 37139482, 2023). "The relationship between CK2 and Hh/Gli1 signaling in mesothelioma is unknown." (PMID 25422081, 2014). "Targeting the Hh pathway either through RNA-interference knockdown of GLI1 and GLI2 or using Gli inhibitors, has been shown to induce growth inhibition and cell death in mesothelioma cells and xenograft tumors in vivo." (PMID 25544756, 2015). "Moreover, our results revealed that mTOR pathway is involved in Cul4A-mediated Gli1 expression in mesothelioma cells, possibility through mTOR activation by Cul4A-mediated proteolysis of mTOR inhibitors and through crosstalk between the activated mTOR pathway and Gli1 pathway." (PMID 26218750, 2015). "We have also observed decreased transcriptional activities of SMO and Gli1 in mesothelioma H28 cells after Cul4A knockdown by siRNA (data not shown), suggesting that SMO is in part involved in the Cul4A-mediated Gli1 expression." (PMID 26218750, 2015). "Among the six mesothelioma samples with negative Cul4A expression, one showed negative Gli1 expression and two showed weak Gli1 expression." (PMID 26218750, 2015). "Among 14 mesothelioma samples with weak Cul4A expression, 28.6% showed negative Gli1 expression and 50% showed weak Gli1 expression." (PMID 26218750, 2015). "RT-qPCR was applied to detect SMO and GLI1 mRNA levels in malignant mesothelioma tissues and normal mesothelial tissues, and statistical analysis showed that SMO and GLI1 mRNA expression levels were significantly higher in mesothelioma tissues than in normal mesothelial tissues (P < 0.05)." (PMID 37139482, 2023). "GLI1 was highly expressed in 27 mesothelioma tissues and upregulated up to 2 fold or more in 22 of the highly expressed samples, 5 cases were not significant, and 3 cases had lower expression in mesothelioma tissues than benign mesothelial tissues." (PMID 37139482, 2023).
ovarian tumors (9 papers, 2011 to 2025). "A somewhat unexpected finding was that activation of TGFBR1 using inducible Gli1-Cre caused ovarian tumor formation." (PMID 27344183, 2016). "The immunohistochemical expression levels of SHH, DHH, PTCH, SMO, and GLI1 proteins in ovarian tumors correlated strongly with malignant features, being higher in carcinomas than in borderline malignant tumors and, to a lesser extent, in benign cystadenomas." (PMID 40565349, 2025). "The Hh pathway-related proteins, including Ptch1 and Gli1 proteins, have been expressed in primary ovarian tumors and cell lines, furthermore, the abnormal activation of this pathway contributes to the malignancy of OC." (PMID 37851362, 2023). "RNAscope in situ hybridization was used to localize the expression of GLI-Kruppel family member GLI1 (Gli1) in ovarian tumor tissues." (PMID 29221447, 2017). "Unexpectedly, we found that constitutive activation of TGFBR1 using GLI-Kruppel family member GLI1 (Gli1)-CreERT2 (designated as TGFBR1-CAGcre) caused the development of INHA-positive ovarian tumors following tamoxifen injection." (PMID 27344183, 2016). "We initiated our investigation by analyzing the expression of both the Hh pathway ligand Shh by immunohistochemistry and the Gli1 transcription factor by real-time PCR in human ovarian tumors." (PMID 22140510, 2011). "We assessed the relative expression of the Hh pathway members Shh and Gli1 in a subset of ovarian tumors." (PMID 22140510, 2011). "Further histochemical and molecular analyses provided evidence of overactivation of TGFBR1 in the granulosa cell compartment during ovarian pathogenesis in TGFBR1-CAG9Cre mice, along with upregulation of Gli1 and Gli2 and downregulation of Tgfbr3 in ovarian tumor tissues." (PMID 29221447, 2017). "This could potentially explain the observation of ovarian tumor development resulting from TGFBR1CA activation by Gli1-Cre." (PMID 27344183, 2016). "Second, ovarian tumors in TGFBR1-CAAcre mice had higher levels of Gli1 and Gli2 mRNAs." (PMID 27344183, 2016). "In addition, we analyzed SHH, SMO, Ptch1, and Gli1 mRNA levels in the 4 individual patient samples we used to generate tumor xenografts for analyzing the effect of Hh pathway inhibition on ovarian tumor growth in vivo." (PMID 22140510, 2011). "A previous study reported that GLI1 and GLI2 mRNA levels, indicators of active HH signaling, were significantly higher in cancer cells isolated from persistent/chemoresistant ovarian tumors than those isolated from matched primary tumors." (PMID 40565349, 2025). "In a previous study, we reported that GLI1 and GLI2 mRNA levels, indicators of hedgehog signaling, were significantly higher in cancer cells isolated from persistent/chemoresistant ovarian tumors compared to those isolated from matched primary tumors." (PMID 25216523, 2014). "Consistent with previous results, GLI1 and GLI3 (HH pathway transcriptional effectors), PTCH1 (HH signaling repressor and target gene), SMO (HH signaling activator), IHH and SHH (HH pathway ligands) were expressed in ovarian tumors, albeit at variable levels." (PMID 26755648, 2016).
soft tissue tumors (9 papers, 2021 to 2025). "The biologic behavior of GLI1-altered soft tissue neoplasms varies from completely indolent to potentially aggressive metastasizing neoplasms." (PMID 38491228, 2024).
colitis (8 papers, 2018 to 2024). Inflammation of the colon. "It has been reported that GLI1 is associated with colitis and promotes colitis-associated tumorigenesis." (PMID 37889976, 2023). "The fate of the CD34+ fibro seven and Gli1+ fibro 13 subsets are less clear in this murine model of colitis." (PMID 39872845, 2024). "Mice with a 50% reduction in Gli1 developed severe intestinal inflammation during DSS treatment compared with WT mice, suggesting that Gli1 protects mice from DSS-induced colitis." (PMID 34702800, 2021). "Besides, TNF-α/NF-κB/JMJD2D has a protective effect against DSS- or AOM/DSS-induced colitis via activation of Hh/Gli1/Gli2." (PMID 34702800, 2021). "Gli1, the major transcription factor of Hh signalling, is a strong candidate gene that maps to the IBD2 locus, and can protect the intestines from damage from IBD-associated DSS-induced colitis." (PMID 34702800, 2021). "Gli1-expressing mesenchymal cells serve as a reserve Wnt source and modulate the Wnt-producing stem cell niche during recovery from DSS-induced colitis in mice." (PMID 34702800, 2021).
diffuse large B-cell lymphoma (8 papers, 2019 to 2022). "MYC-regulated NEAT1 was found to promote diffuse large B cell lymphoma (DLBCL) proliferation via the miR-34b-5p-GLI1 pathway." (PMID 34295338, 2021). "The tumor driver NEAT1 acts as a ceRNA to regulate the miR-34b-5p-GLI1 axis, further affecting the proliferation of diffuse large B-cell lymphoma." (PMID 33820555, 2021). "A study using diffuse large B cell lymphoma cells revealed that ABCG2 is a transcriptional target of the hedgehog signaling transcription factor GLI1." (PMID 31083682, 2019). "For example, it was found that MYC-regulated NEAT1 promoted diffuse large B-cell lymphoma (DLBCL) proliferation via the miR-34b-5p-GLI1 pathway, which could provide a novel therapeutic target for DLBCL." (PMID 35127729, 2021).
cholangiocarcinoma (7 papers, 2011 to 2024). A carcinoma that arises from the intrahepatic biliary tree (intrahepatic cholangiocarcinoma) or from the junction, or adjacent to the junction, of the right and left hepatic ducts (hilar cholangiocarcinoma). "Gli1 is responsible for increased SOX2 expression in cholangiocarcinoma under hypoxia conditions and promotes cancer cell stemness, epithelial-to-mesenchymal transition and invasion." (PMID 33499351, 2021). "EHF plays a crucial role in promoting cholangiocarcinoma (CCA) by activating GLI1 transcription." (PMID 38741887, 2024). "Both mutation and copy number alterations (CNA) affecting Hedgehog pathway main members, namely GLI1, GLI2, GLI3, SMO, PTCH1/2, SUFU, and DHH, have been observed in mixed cholangiocarcinoma patients with different frequencies." (PMID 34638259, 2021). "Altogether, the reported studies provide a role for the Hedgehog-GLI signaling pathway, particularly for GLI1 and GLI2, as reliable prognostic factor for cholangiocarcinoma." (PMID 34638259, 2021). "However, based on our RNA-seq data, the KAT2B/GLI1/BCL2 pathway is not applicable in cholangiocarcinoma." (PMID 38641672, 2024). "GLI1, as in other tumors, was found to promote iCCA survival, growth, and EMT reprogramming, together with GLI3, which directly binds to the promoter of death receptor 4 (DR4), repressing its transcription and thus preventing TRAIL-dependent cholangiocarcinoma cell death." (PMID 34638259, 2021).
craniosynostosis (7 papers, 2017 to 2025). Craniosynostosis is defined as the premature fusion of one or more cranial sutures leading to secondary distortion of skull shape resulting in skull deformities with a variable presentation. "These Gli1+ cells are integral to suture maintenance and their loss precedes suture fusion in the Twist1+/− mouse model of craniosynostosis." (PMID 35451466, 2022). "In utero exposure to the serotonin selective reuptake inhibitor citalopram increased the incidence of craniosynostosis in mice and reduced the number of Gli1+ MSCs in the sutures." (PMID 35451466, 2022). "Our study provides the original evidence of the presence of a GLI1+ MSC subpopulation in the craniofacial bone specimens of patients suffering from nonsyndromic craniosynostosis." (PMID 32575385, 2020). "GLI transcription factors emerge as critical nodal points, where mutations trigger severe developmental defects, GLI3 dysfunction causes craniosynostosis and calvarial hyperossification, while GLI2/GLI1 perturbations underlie syndromic conditions like Pallister‐Hall and Greig cephalopolysyndactyly." (PMID 40857061, 2025). "Ablation of GLI1 +SuSCs leads to craniosynostosis, a premature closure of cranial sutures resulting in arrested skull growth, while impaired cell proliferation and osteogenic differentiation of SuSCs is associated with wide-open fontanels due to reduced or delayed bone growth." (PMID 36656123, 2023). "In addition, ablation of Gli1+ SuSCs by using Gli1-CreERT2;DTAflox/flox mice results in the typical phenotype of craniosynostosis, which is mediated via diphtheria toxin fragment A (DTA) under the inducible Cre-loxP system." (PMID 34439795, 2021). "GLI1-positive cells in the suture mesenchyme are a source of mesenchymal stem cells, and ablation of Gli1 in postnatal mice results in the premature fusion, or craniosynostosis, of all the calvarial sutures and the consequent secession of growth." (PMID 29311969, 2017). "It has been suggested that the role of RAB23 in the pathogenesis of craniosynostosis involves negative regulation of both FGFR and Hedgehog–GLI1 signaling, which are involved in osteoprogenitor cell recruitment and stem cell maintenance within the sutures." (PMID 35451466, 2022). "In contrast to the ablation of Gli1+ cells, that of Prrx1+ cells does not result in a craniosynostosis phenotype, indicating that Prrx1+ cells of the suture are dispensable for postnatal calvarial development." (PMID 35451466, 2022).
endometriosis (7 papers, 2017 to 2023). The growth of functional endometrial tissue in anatomic sites outside the uterine body. "Both SIRT1 and BCL6 bind to the GLI1 promoter and suppress its expression, leading to a reduction in GLI in women with endometriosis." (PMID 37108154, 2023). "Sonic hedgehog (SHH) and its downstream signalling transcription factor GLI1 are upregulated in the eutopic endometrium of women with endometriosis in comparison to healthy controls." (PMID 32977859, 2020). "GLI1 expression is increased in the endometrium of women with endometriosis in comparison to healthy controls, and in ovarian endometriomas but expression in human lesions at other sites is yet to be assessed." (PMID 32977859, 2020). "Hedgehog signalling genes Shh, Gli1, Stil1 and Jag2 are also upregulated in the ectopic lesions of a mouse model of endometriosis featuring enhanced lesion formation." (PMID 32977859, 2020). "Further, elevated levels of SIRT1 and BCL6 in secretory phase endometrium of women with endometriosis likely accounts for the decrease noted in GLI1 protein expression, as a sign of P4 resistance." (PMID 28754906, 2017). "In eutopic endometrium, GLI1 expression is reduced in women with endometriosis." (PMID 28754906, 2017). "Gli1+ marks perivascular MSC-like cells that contribute to organ fibrosis and in endometriosis, the immune environment of the peritoneal cavity can stimulate fibrosis through smooth muscle metaplasia (SMM) of endometrial stromal cells." (PMID 35725766, 2022). "SHH, SMO, GLI1 and GLI3 expression was strongly increased with clinical stages in the eutopic endometrium, which suggested that the SHH signaling pathway was abnormally activated in endometriosis." (PMID 35933378, 2022). "In turn, reduced expression of GLI1 was shown in the endometrium of women with endometriosis, confirming a mechanistic role for STAT3, BCL6, and SIRT1 overexpression in the P4 resistance of endometriosis." (PMID 31387263, 2019). "Our immunohistochemistry analysis found that GLI1 protein levels are significantly reduced, specifically in the endometrial epithelial cells comparing women with and without endometriosis." (PMID 28754906, 2017). "Therefore, we examined GLI1 expression in eutopic endometrium from women with (n = 20) and without (n = 13) endometriosis by immunohistochemistry." (PMID 28754906, 2017).
metastatic disease (7 papers, 2007 to 2023). "The Hh signaling pathway has been reported to be activated in a number of human tumors, including NSCLC and metastatic disease and ultimately activates the transcription factor human glioma-associated oncogene homolog 1 (Gli1)." (PMID 25586417, 2015). "Less equivocal is the role of GLI in advanced PCa: high levels of GLI1 mRNA have beendescribed in metastatic tumours and both GLI1 and GLI2 have been linked withandrogen-independence." (PMID 21633508, 2011). "It has recently been suggested that oncogenic GLI1 progresses during colon carcinogenesis and in metastatic disease, whereas in normal colonic tissue, Hh-GLI is strictly involved in differentiation." (PMID 34113570, 2021). "Karhadkar reported that Shh and Ihh were both expressed in localized prostate cancer and benign tissue but that the Hh target genes Ptc and Gli1 were expressed only in metastatic tumors." (PMID 17343742, 2007). "Overexpression of Gli1, a downstream transcription factor of the Hedgehog signaling pathway, is observed in many cancers and is suggested to play a role in the development and progression of metastatic diseases." (PMID 26988754, 2017). "The results of the present study suggest that inhibition of Gli1 may serve as a useful strategy to target metastatic disease in patients with NSCLC." (PMID 25586417, 2015).
osteoporosis (7 papers, 2018 to 2025). A condition of reduced bone mass, with decreased cortical thickness and a decrease in the number and size of the trabeculae of cancellous bone (but normal chemical composition), resulting in increased fracture incidence. "They observed a significant reduction in bone volume and severe osteoporosis in the craniofacial bone after eight months of induction, which was reversed by India Hedgehog (Ihh) agonist treatment, which upregulated Gli1 activity." (PMID 37759749, 2023). "In addition, ablation of Gli1+ MSCs leads to skull growth blockade, osteoporosis, and impaired repair." (PMID 37759749, 2023). "Therefore, the rescue effect of teriparatide on GC-induced osteoporosis may function through Gli1+ MMPs but in distinct differentiation statuses." (PMID 38673956, 2024). "Deleting Gli1 Lineage using cre-inducible diphtheria toxin A (DTA) in one-month-old Gli1-CreERT2;DTAflox/flox mice led to coronal and frontal-premaxilla suture fusion after 1-month induction and all craniofacial sutures fusion after 2-month induction with skull growth arrest and osteoporosis." (PMID 37325554, 2023). "Blocking the Hh pathway through the specific deletion of Ptch1 in HOC+ mature osteoblasts leads to severe osteoporosis, and the deletion of SMO in Osx+ or Gli1+ osteogenic progenitors also results in decreased bone formation." (PMID 40141354, 2025). "Importantly, the OB cluster of Gli1+ MMPs is dramatically decreased in response to MPS analyzed by scRNA-seq and lineage tracing experiments indicating the OB cluster is a potential cell type mediating MPS-induced osteoporosis." (PMID 38673956, 2024).
brain cancer (6 papers, 2013 to 2024). A primary or metastatic malignant neoplasm affecting the brain. "Furthermore, the activation of AMPK triggers the interaction between β-TrCP and Glioma-associated oncogenes (GLI1), which induces β-TrCP-mediated GLI1-ubiquitination and degradation in human brain cancer cells." (PMID 35248054, 2022). "Suppression of GLI1/GLI2 reduced hTERT protein levels in human colon, prostate and brain cancer cells." (PMID 24086482, 2013). "Suppression of both GLI1 and GLI2 functions reduced hTERT mRNA and protein expression in human colon, prostate and brain cancer cell lines." (PMID 24086482, 2013).